KLF5 (KLF transcription factor 5)
Diseases named in the same sentence as KLF5 in open-access papers (continued):
Sharing a sentence is not in itself a finding about the gene and the disease.
tumor (211 papers, 2008 to 2026). "Given the established association between Vimentin and tumor cell malignancy in numerous studies, Vimentin was chosen as the downstream gene of KLF5 in conjunction with RNA-seq data." (PMID 40307891, 2025). "For instance, KLF4 is often associated with tumor suppression, while KLF5 has been linked to promoting tumor growth in breast cancer." (PMID 40860800, 2025). "Exosomal lncRNA NEAT1 secreted by M2 polarized tumor‐associated macrophages promotes HCC immune escape by recruiting KLF5 and upregulating galectin‐3." (PMID 39720765, 2025). "We discovered that KLF5 is implicated in tumor progression and are prognostic markers across pan-cancer." (PMID 41583492, 2025). "In some cases, KLF5 overexpression has been linked to unfavourable outcomes such as increased tumour growth, poor prognosis and resistance to chemotherapy." (PMID 37461162, 2023). "STAT3 is a tumor promoter that helps tumor cells evade natural killer cell-mediated immune surveillance, and KLF5 is also associated with it." (PMID 36761967, 2023). "KLF5 expression is associated with poor outcomes in OC patients and can drive tumor progression in vitro and in vivo." (PMID 37702443, 2023). "In this study, we found that KLF5 deficiency inhibits progressive tumor growth and enhances antitumor immunity in a CD8+ T-cell-dependent manner." (PMID 36923542, 2023). "Tumor cells expressing the Ac-KLF5-mimicking mutant KLF5K369Q (KLF5KQ or KQ) caused bone metastatic lesions and became resistant to docetaxel in mouse models while maintaining a mesenchymal phenotype and tumorigenicity." (PMID 33731701, 2021). "KLF5 has been found to play an oncogenic role, where it is associated with tumor progression, aggressive clinical behavior and poor survival." (PMID 33430300, 2021). "Overexpression of KLF5 has been associated with poor survival and tumor progression in various cancers." (PMID 33430300, 2021). "Further, KLF5 often acts as tumor suppressor and its loss has been involved in several aspects of cancer progression, including tumor initiation." (PMID 34062049, 2021). "Consistent with a previous report 26, this suggests wild type KLF5 and acetylation deficient KLF5 promote tumor growth while acetylated KLF5 inhibits tumor growth." (PMID 32685011, 2020). "In this study, the in vitro experiment confirmed the tumour suppression function of KLF5 in PC‐3 and 22RV1 cell lines, and the DNA methylation inhibitor demethylated and caused re‐expression of KLF5." (PMID 32281273, 2020). "The highly expressed ARHGDIG in the KLF‐P group leads to a poor prognosis of PCa (P = .00028), and the expression of ARHGDIG in tumours is negatively associated with the KLF5 levels (R = −0.34, P < .001), confirming the prognostic value of KLF5 in PCa." (PMID 32281273, 2020). "Clinically KLF5 has been found to play an oncogenic role where it is associated with tumor progression, aggressive clinical behavior and poor survival." (PMID 33424607, 2020). "In GC patients, high levels of KLF5 in CAFs were closely associated with clinical pathological features such as tumor size, invasion depth, cell grade, and lymph node metastasis, as well as poor prognosis." (PMID 29772686, 2018). "The underlying mechanisms that how KLF5 has a tumor suppressor role in ccRCC need to be further studied." (PMID 28749461, 2017). "Klf6 has been characterized as a tumor suppressor in prostate, ovary, liver, and gut, and Klf4, Klf5, and Klf6 are also implicated as regulators of viability." (PMID 27213272, 2016). "Klf6 has previously been studied as a tumor suppressor in prostate, ovary, and liver, and Klf4, Klf5, and Klf6 are also implicated as regulators of viability." (PMID 27213272, 2016).
tumor (continued). "The increase in angiogenesis correlated with the increase in tumor mass and the decrease in Klf5 expression caused by Klf5 deletion in the same mice." (PMID 25896712, 2015). "Chromosomal deletion is a hallmark of tumor suppressor genes, and the locus spanning the KLF5 gene, 13q21, is the second most frequently deleted chromosomal locus in over 70 types of human malignancies." (PMID 23755247, 2013). "Deletion of Klf5 was insufficient to initiate neoplasia, although deletion of one Klf5 allele promoted cell proliferation and caused hyperplasia." (PMID 23755247, 2013). "Our findings indicate that infection with H. pylori increases populations of murine gastric epithelial cells expressing both KLF5 and Lrig1, proteins implicated in tumor biology and stemness." (PMID 23372710, 2013). "The deletion of one of the Klf5 alleles in ApcMin/KRASV12 mice reduced the average tumor number to 19 per mouse - a 92% reduction." (PMID 20298593, 2010). "Further in the mouse model of intestinal tumorigenesis, haploinsufficiency of KLF5 rescues the tumor initiating effect of the ApcMin mutation in the intestine." (PMID 20514221, 2009). "In addition, KLF5 promotes the growth of tumor-associated fibroblasts, a type of cell thought to have an essential role in tumor angiogenesis." (PMID 36761967, 2023). "Loss of either KLF5 or SOX9 inhibits SCC tumor progression in nude mice." (PMID 34298613, 2021). "Interestingly, loss of KLF5 or interruption of KLF5 acetylation at K369 significantly attenuated tumor formation in the tibia, as the incidence of tumor formation for KLF5–/– or KLF5KR was less than that for KLF5 or KLF5KQ." (PMID 33731701, 2021). "Therefore, more extensive metastatic tumor formation and more severe bone lesions caused by the acetylation of KLF5 at K369 are caused by reasons other than tumor cell proliferation rate." (PMID 33731701, 2021). "Posttranslational modifications of proteins, including the acetylation of KLF5, are reversible, which implies that when a stress is withdrawn, mesenchymal cancer cells could become epithelial and rapidly proliferate, causing tumor recurrence and faster growth." (PMID 33731701, 2021). "KLF5 overexpression was seen in more than 53% of the patient samples and was significantly associated with aggressive clinico-pathological criteria including larger tumor size, distant metastasis, stage IV tumors and poor patient survival." (PMID 33424607, 2020). "In understanding how KLF5 loss enhances tumor angiogenesis, our Gene Ontology (GO) enrichment analysis of differentially expressed genes upon Klf5 deletion identified blood morphogenesis as the most affected biological process, involving a molecular signature of activated pro-angiogenic genes." (PMID 25896712, 2015). "It indicates that determining whether KLF5 acts as an oncogene requiring amplification or a context-dependent tumor suppressor susceptible to loss is essential for understanding its pathobiology in a given tumor." (PMID 41583492, 2025). "Additionally, these mice inoculated with control or Klf5-deficient EMT6 cells experienced complete tumor remission, then they were rechallenged with EMT6 cells or CT26 cells, and they were resistant against EMT6 cells but facilely developed CT26 tumors, suggesting that they formed immune memory." (PMID 36923542, 2023). "However, some data show that elevated expression of KLF5 is associated with increased tumor-infiltrating immune cells and suggest that upregulation of KLF5 may be linked to a better prognosis in CRC." (PMID 37173904, 2023). "Therefore, hemizygous deletion, which causes haploinsufficiency of Klf5, could be a common tumor promoting event." (PMID 23755247, 2013). "This immune-derived signaling potentially converged on KLF5-positive tumor cells, with KLF5 identified as a putative transcriptional activator of USP54." (PMID 41929495, 2026).
tumor (continued). "The identification of transcription factors such as BPTF, SOX4, and KLF5 in ITGB8-high cells further implicates these factors in regulating tumor–stroma interactions and mediating the aggressive phenotype associated with a high MTSR." (PMID 41602481, 2026). "Accumulating evidence has demonstrated that FBW7 acts as a crucial tumor suppressor by mediating the degradation of multiple substrates, including KLF5." (PMID 39827156, 2025). "Krüppel-like factor 5 (KLF5) is involved in various aspects of tumor development, metastasis, and drug resistance through their regulation of transcription and translation, yet its functions in a comprehensive cancer framework are still unclear." (PMID 41583492, 2025). "In this study, significantly high KLF5 expression in the HCC group was associated with TNM stage, tumor size, AFP level, portal vein thrombosis, HBV infection, and the 5-year survival rate of HCC patients." (PMID 40697993, 2025). "The study suggested that TGF-β/SMAD–induced acetylation of KLF5 acts as a barrier to tumor progression, in part by restraining excessive FGFR1 signaling." (PMID 41514658, 2025). "Pharmacologic inhibition of RUVBL1/2 ATPase activity disrupts this interaction, impairs KLF5 function, and suppresses tumor cell proliferation." (PMID 41241675, 2025). "Deacetylated KLF5 also upregulated CX3CR1 expression in tumor cells, further amplifying FGF9-driven FGFR1 activation." (PMID 41514658, 2025). "At the preclinical research and translational application level, KLF5 inhibitors have shown broad tumor type adaptability and potential for combination therapy." (PMID 41583492, 2025). "Deacetylated KLF5 increased TNF-α secretion by tumor cells, which in turn drove iCAFs toward an earlier, high-FGF9–secreting state, establishing a TNF-α–FGF9 reinforcing loop with Krt4+ cancer cells." (PMID 41514658, 2025). "In both tumor models, KLF5 knockout reduced tumor growth and extended animal survival, confirming its requirement for tumor formation." (PMID 41241675, 2025). "CircEZH2 promotes tumor cell proliferation and metastasis in vitro and in vivo by acting as a molecular sponge for miR-217-5p, thereby increasing Krüppel-like factor (KLF5) protein levels." (PMID 40740236, 2025). "Oxaliplatin combined with KLF5 inhibitor significantly potentiated cell death in vitro and inhibited tumor growth in vivo compared with either treatment alone." (PMID 39827156, 2025). "Aberrant KLF5 expression is involved in tumor biological activity, induces pluripotent stem cells, and maintains an embryonic stem cell state." (PMID 40697993, 2025). "We found that KLF5 had lower expression in metastatic tumours versus primary tumours and normal tissue, hence potentially acting as a tumour/metastatic suppressor, whereas SP1 displayed the opposite pattern, functioning likely as a tumour/metastatic promoter." (PMID 39748426, 2025). "KLF5 has been shown to play an oncogenic role in various malignant tumors by indirectly affecting tumor growth, proliferation, malignant metastasis, and the maintenance of tumor microenvironment homeostasis through the regulation of signaling pathways." (PMID 40936898, 2025). "As a potent driver of tumor progression and metastasis, KLF5 accelerates the cell cycle, suppresses apoptotic signals, and promotes epithelial-mesenchymal transition to enhance invasive potential." (PMID 41583492, 2025). "Our work confirms that KLF5 plays distinct, context-dependent roles in different tumor types, yet its targeted inhibition emerges as a consistently viable therapeutic strategy." (PMID 41583492, 2025). "Endpoint tumor analysis revealed that KLF5 function was restored in each tumor despite effective knockout at the time of transplantation." (PMID 41241675, 2025). "The relationship between KLF5 expression and the tumor immune landscape was assessed across diverse malignancies." (PMID 41583492, 2025).
tumor (continued). "IL-8 is a chemokine known to promote endothelial proliferation, migration, and vascular remodeling, while KLF5 is a zinc finger transcription factor involved in angiogenesis and tumor progression through regulation of multiple downstream targets." (PMID 40943311, 2025). "To investigate the functional impact on GBM tumor cells of KLF5, we conduct in vitro validation by using GBM cell lines." (PMID 41583492, 2025). "Collectively, our data reveal a hitherto unrecognised role of KLF5 in promoting genome stability and suggest KLF5 as a therapeutic target for ARID1A-deficient tumours." (PMID 39779698, 2025). "Consistently, in vivo animal experimental results also showed that KLF5 promotes tumor growth through XPO1, at least in part." (PMID 39888288, 2025). "KLF5 plays a role in stromal regulation of tumor progression via the CCL5/CCR5 axis, a tumor escape mechanism by instrumentalizing the immune cell compartment." (PMID 40465055, 2025). "To validate the predictive capacity of KLF5 in tumor immunotherapy, we performed ROC analysis of pan-cancer immunotherapy cohorts from the GEO database, demonstrating its modest predictive efficacy for immunotherapeutic response." (PMID 41583492, 2025). "Silenced NEDD4L facilitated ESCC cell proliferation, migration and invasion and inhibited apoptosis in vitro, and accelerated tumour growth in vivo, while KLF5 inhibition produced an opposite effect." (PMID 39317954, 2024). "In line with tumor suppressors and oncogenes being a major feature explaining aneuploidy patterns, we identified KLF5 as a colorectal-specific dependency gene." (PMID 38622679, 2024). "We did not observe metastasis in the bone, liver, or lungs of PBCreKlf5KR/KRPten–/– mice within 1.5 years, indicating a role of deAc-KLF5 in suppressing tumor motility." (PMID 38781024, 2024). "The overexpression of KLF5 in tumor tissues was validated by western blotting, and the body weights of the mice were monitored." (PMID 37588224, 2024). "According to our results, potential strategies to overcome the challenges posed by spatial heterogeneity, such as combination therapies or localized delivery methods, to enhance the targeting of the NEDD4L/KLF5 axis across different tumour regions." (PMID 39317954, 2024). "KLF5 was reported to be tumor-suppressive in the context of several cancer types, such as breast and prostate." (PMID 38622679, 2024). "By acting downstream of miR‐9, KLF5 participates in tumour growth and cancer resistance to radiotherapy + Cetuximab in vitro and in vivo." (PMID 39317954, 2024). "Recent researches have revealed that KLF5 promotes tumour progression and Parp inhibitor resistance in ovarian cancer." (PMID 39317954, 2024). "Consistently, Klf5KR knockin in the GEMM further confirmed the suppressive function of KLF5 acetylation in primary tumor growth." (PMID 38781024, 2024). "Deacetylated KLF5 promoted tumor cells to secrete TNF-α, which stimulated inflammatory CAFs to release FGF9." (PMID 38781024, 2024). "Emerging evidence has demonstrated that FBW7 acts as a vital tumor suppressor by targeting multiple oncogenic substrates in which the expression of KLF5, another key substrate, is also significantly regulated by FBW7." (PMID 38433576, 2024). "Inhibition of STK24 expression decreased the ability of KLF5 to promote tumor proliferation and metastasis." (PMID 37181807, 2023). "Taken together, the results demonstrated that Klf5 contributes to accelerating tumor growth partly by impairing the infiltration of Cd8+ T cells." (PMID 36923542, 2023). "Mice with EMT6 or CT26 tumors were unresponsive to anti-Pd1 monotherapy, while the anti-Pd1 blocker resulted in obvious tumor regression and prolonged survival in mice with Klf5 KD tumors." (PMID 36923542, 2023). "Depletion of Klf5 in EMT6 cells substantially retarded tumor growth, while tumors derived from 67NR cells overexpressing Klf5 grew faster than those from control cells." (PMID 36923542, 2023).
tumor (continued). "For example, miR-217 has been validated to repress tumor growth and liver metastasis by targeting Kruppel-like factor 5 (KLF5) to activate the mTOR-PI3K-AKT pathway." (PMID 37626035, 2023). "To address the necessity of Klf5/Cox2 axis for tumor immunity regulation, we developed subcutaneous tumor mouse models with 67NR wt/Klf5-OV cells." (PMID 36923542, 2023). "Compared to ApcMin/+ mice, ApcMin/+/Lpar2−/− mice exhibited decreased tumor progression and hypoxia in response to reduced expression of Klf5, Ctnnb1, Ccnd1 and c-Myc." (PMID 37173904, 2023). "KLF5 is also a mediator of the inhibitory effects of the TGF-β signaling on cancer that TGF-β/SMAD4 signal inhibits the transcription of KLF5 that, in turn, switches Sox4 from tumor promoter to suppressor." (PMID 36761967, 2023). "circCRKL was revealed to act as a tumor suppressor in PC by binding miR-141, leading to the upregulation of miR-141 target KLF5, repressed cell cycle, invasion, migration, boosted apoptosis of PC cells, and reduced tumor progression in vivo." (PMID 37511619, 2023). "Cxcr6 is a classical biomarker of resident memory CD8+ T (Trm) cells to sustain tumor control 41, 42, and our results demonstrated that Klf5 deletion specifically promoted the infiltration of Cd8+Cxcr6+ T cells in tumors." (PMID 36923542, 2023). "Here, we show that KLF5 is upregulated in ESCC, where its level was significantly associated with tumor differentiation and lymph node metastasis status." (PMID 38087142, 2023). "KLF5 activates EMT in tumor tissues through PI3K/AKT/Snail signaling pathway, and high expression of KLF5 is associated with tumor metastasis and poor prognosis." (PMID 36761967, 2023). "Curiously, depending on the disease stage, as in the case of KLF4 and KLF5, their role can switch between oncogene and tumor suppressor." (PMID 37239940, 2023). "For this analysis, the Cox2 levels in tumors carrying Klf5 KD tumor cells were lower than those in the control group." (PMID 36923542, 2023). "eEF2 and phosphorylated eEF2 are prognostic indicators of HCC patient survival, and that eEF2 kinase promotes HCC angiogenesis and tumor progression through SP1/KLF5-mediated VEGF expression." (PMID 37740172, 2023). "High expression of KLF5 was also found in short-surviving PDAC patients and associated with shorter overall and tumor-free survival times." (PMID 37239940, 2023). "Collectively, the key findings of this study demonstrated that KLF5 promoted tumor proliferation and metastasis in ESCC cells." (PMID 38087142, 2023). "The re-expression or abnormal dysregulated expression level of stemness genes, like oct4, sox2, klf4 and klf5, in differentiated cells are a common feature of the tumorigenesis process and have been well documented in many tumor types." (PMID 38137514, 2023). "For example, Klf5 haploinsufficiency in ApcMin/+/KrasG12V mice resulted in significantly reduced tumor number and size compared to ApcMin/+ mice." (PMID 37173904, 2023). "Mechanistically, KLF5 exerts its tumor promotion effect by up-regulating fibroblast growth factor binding protein 1 (FGF-BP1) and snail family transcriptional repressor 2 (SNAIL2)." (PMID 38087142, 2023). "Compared to para-tumor specimens, the mRNA levels of KLF5, KLF7, KLF8, and KLF13 were elevated, whereas those of KLF4, KLF6, and KLF10 were reduced in HCC specimens." (PMID 37554278, 2023). "Mechanistically, KLF5 binds to the promoter of the COX2 gene and promotes COX2 transcription; subsequently, KLF5 deficiency decreases prostaglandin E2 (PGE2) release from tumor cells by reducing COX2 expression." (PMID 36923542, 2023).